HIF1A (hypoxia inducible factor 1 subunit alpha)
Diseases named in the same sentence as HIF1A in open-access papers (continued):
Sharing a sentence is not in itself a finding about the gene and the disease.
tumor (continued). "To assess whether the reduced hypoxia response in tumor cells alters hypoxia in HIF-1α-KD tumors, we injected pimonidazole, which forms covalent adducts if the oxygen partial pressure falls below approximately 10 mm Hg." (PMID 33142239, 2020). "Importantly, overexpression of HIF-1α has been positively correlated with tumor progression and poor prognosis in patients with GBM." (PMID 32045997, 2020). "This information presents hypoxia and upregulated HIF1-α as possible contributors to taxane resistance in CRPC, yet more research must be done on the frequency of hypoxia and the basal HIF1-α levels of the tumor before considering them to be therapeutic targets." (PMID 33182737, 2020). "Both HIF-1α and SP1 were positively associated with tumor metastasis (P<0.001)." (PMID 31892989, 2020). "In addition, the expression of Glut-1, which is a key vector of glucose metabolism, is mainly regulated by HIF-1α to meet the energy needs of tumor growth." (PMID 32493238, 2020). "An example is miR-210, whose levels increase through the actions of HIF-1α and has as its target a great variety of enzymes involved in mitochondrial metabolism, favouring the metabolic reprogramming of these tumours, evading apoptosis or participating in angiogenesis among other functions." (PMID 32872155, 2020). "On the other hand, drugs targeting HIF-1α mediated metabolic enzymes may also affect tumor cell proliferation induced by hypoxia." (PMID 32928258, 2020). "Further investigations revealed that HBB was able to increase cancer aggressiveness through HIF-1α, that it was increased in primary tumours of higher grade, and that blocking its oxygen-binding ability could abrogate some of the phenotypical effects observed." (PMID 32527062, 2020). "Additionally, hypoxia can enhance MDSC migration to the tumor site directly via HIF-1α-mediated chemokine production." (PMID 32316260, 2020). "Hypoxia is a key feature leading to tumour progression driven by hypoxia‐inducible factor (HIF)‐1α." (PMID 32065498, 2020). "HMGB1‐modulated HIF‐1α signaling pathway can promote angiogenesis and tumor migration." (PMID 32436353, 2020). "HIF1A is the most important transcriptional factor in tumor survival under hypoxic conditions." (PMID 32127518, 2020). "Moreover, the tumor-immunosuppressed programmed death ligand 1 (PD-L1) is expressed via HIF-1α and STAT3 under hypoxic conditions in lung cancer." (PMID 32823915, 2020). "In other malignancies, however, HIF1α has an established tumor-promoting role." (PMID 33077781, 2020). "Hypoxia was typically associated with many types of solid tumors, Hypoxia-inducible factor-1 (HIF-1) was a principle modulator of the tumor cell response to hypoxia, and HIF-1α level was normally kept low by proteasomal degradation, it rapidly stabilized under conditions of hypoxia." (PMID 32054470, 2020). "In our experiments, we found that after 3‐7 days of intervention, low‐dose apatinib significantly reduced the expression of HIF‐1α in the transplanted tumor tissue, the α‐SMA level in the pericytes was significantly elevated, and the vascular basement membrane was intact." (PMID 32073228, 2020). "Analyses of RNA sequencing revealed that the mRNA levels of many cytokine-encoding genes are upregulated in tumours compared to normal cortex, but none of these genes were differentially regulated by HIF-1α or HIF-2α." (PMID 32807776, 2020). "Furthermore, HIF1α within cancer cells promotes myeloid derived suppressor cells (MDSCs) in the tumor microenvironment." (PMID 33077781, 2020). "Hence, the identification of the Rab5GEF ALS2 as a HIF-1α target gene prompted us to evaluate the impact of ALS2 induction in tumor cell migration, invasion and metastasis." (PMID 33339852, 2020). "Serum HIF‐1α is a regulatory factor with a decisive effect in hypoxic tumor cells." (PMID 31568612, 2020).
tumor (continued). "MCT4, a promoter of the cell export of L-lactate and ketone bodies from glycolytic cells (tumor-associated fibroblasts), is regulated by HIF-1α under hypoxic conditions or when ROS levels increase; then, MCT1 captures and uses this fuel for growth and tumor progression." (PMID 32707662, 2020). "Modulation of HIF-1α leads to another important effect of resveratrol as an anti-tumor agent." (PMID 32331450, 2020). "ccRCC tumours frequently lose one copy of HIF1A and less frequently gain one copy of HIF2A." (PMID 32807776, 2020). "Besides inhibiting directly tumor growth, some inhibitors of HIF-1α transcriptional program, such as YC-1, BAY87-2243, dutasteride, and emetine have shown chemosensitizing effects in solid and hematologic tumors at preclinical levels." (PMID 33291643, 2020). "Furthermore, overactivation of NF-κβ and HIF-1α leads to proliferation, migration, and invasion at the tumor site." (PMID 31906321, 2020). "Additionally, HIF1α stimulates the formation of new blood vessels that supply the tumor with oxygen and nutrients by inducing the expression of the angiogenetic growth factors VEGF and PDGFβ." (PMID 32610612, 2020). "As HIF-1α induces the expression of genes related with tumor survival, we assessed the mRNA levels of CCND2, VEGF, BNIP3L, and CA9, and found that CCND2, VEGF, BNIP3L, and CA9 were upregulated when spheroids were treated with OA, whereas their mRNA levels decreased upon FABP5 or HIF-1α silencing." (PMID 33128030, 2020). "Very recently, HIF-1α deficiency has been linked to reduced tumor growth, which was associated with non-productive angiogenesis and increased NK cell activity." (PMID 33260925, 2020). "We unravel that chronic adrenergic stimulation triggers the upregulation of both GRK2 and HuR protein levels, increases cytoplasmic HuR and fosters nuclear HIF-1α presence, thus, mimicking a pseudo-hypoxia situation that might contribute to tumor progression." (PMID 32413989, 2020). "Though the role of A3R-mediated upregulation of HIF-1α is unclear, these data suggest A3R may both suppress and promote tumor progression." (PMID 32351498, 2020). "Thus, the interference with the HIF-1α response in tumor cells leads to vessel normalization despite the intact hypoxia response in the tumor microenvironment." (PMID 33142239, 2020). "However, under the hypoxic conditions found within a tumor tissue, HIF1α is stabilized and regulates the transcription of its many target genes that contribute to tumor growth through increased cell proliferation and neovascularization." (PMID 32426078, 2020). "Oral administration of AE for 4 weeks caused a significant regression of mouse xenograft tumor (>60%) that derived from OV4855 cells and decreased the expression of endothelial cell antigen-CD31, HIF-1α, IGF1R and SNAIL1 and increased the expression of E-cadherin in tumor tissues." (PMID 32194804, 2020). "Activation of HIF1A signaling may occur within some cells in the primary tumor or in other metastatic sites, generating CTCs with increased ability to proliferate in the brain." (PMID 33298946, 2020). "Accumulating evidence shows that LNT is a critical switch on immunoregulation in tumor development; thus, it may be hypothesized that LNT-induced decreased HIF-1α is partly through tumor immunosuppression." (PMID 33245358, 2020). "Immunofluorescent staining showed that the tumor treated with ICG‐PtMGs@HGd exhibited significant lower content of HIF‐1α compared to the one treated with saline or ICG‐MGs@HGd, suggesting that the hypoxia of the tumor tissue was successfully alleviated due to the catalytic effect of Pt enzyme." (PMID 32995114, 2020). "Previously, TRAF6 overexpression in tumor cells had been shown to stabilize HIF-1α." (PMID 33142239, 2020).
tumor (continued). "This latter experiment argues against the idea that removal of HIF-1α activity in an established mouse ccRCC tumour, to mimic the loss of HIF-1α function that arises as a later event in tumour progression in a subset of human ccRCCs, has a potent effect on tumour aggressiveness." (PMID 32807776, 2020). "The inhibition of HIF1α enzyme is a promising therapeutic target in several tumor types." (PMID 32117717, 2020). "It was found that the expression of HIF-1α in the tumor tissues of the five groups (83.33%) was significantly higher than that in the adjacent tissues, and the expression of Nur77 in the four tumor tissues (66.67%) was significantly higher compared with that in the adjacent tissues." (PMID 33245358, 2020). "That L-AA functions as an enzyme cofactor for Fe2+-2-oxoglutarate-dependent dioxygenases suggests that fine tuning of the intracellular ascorbate levels may limit the expression of HIF-1α and angiogenic proteins, which promote tumor growth and poor outcome." (PMID 33014789, 2020). "Moreover, expression changes in CD105, TGFβ1, VEGF, HIF-1a and tumor vasculature in the presence of low and high doses of bevacizumab in nude mouse models and clinical specimens require further elucidation." (PMID 32587778, 2020). "The autocrine effect of HIF1α‐induced VEGF expression in ECs is important for tumor angiogenesis." (PMID 31885126, 2020). "Since HIF1α was found to be upregulated in tumor cells after Doxo treatment, the down-regulation of HIF1α by SFN could represent a relevant mechanism to enhance Doxo efficacy in cancer cells." (PMID 32425794, 2020). "Therefore a lower R2∗ value indicated more effective anti-cancer treatment in Group D. What’s more, R2∗ value revealed the highest correlation with HIF-1α (r = 0.721), a pathological indicator for evaluating tumor hypoxia." (PMID 33134165, 2020). "In addition, the regulatory effect of HIF1A on tumour metabolism and pro-angiogenic effects were demonstrated by bioinformatics analysis and cytology experiments." (PMID 33218358, 2020). "Immunostaining of tumor sections from 45 patients with PNETs showed that well-differentiated tumors had high cytoplasmic expression of VEGF and HIF-1α, whereas poorly differentiated carcinomas were associated with nuclear HIF-1α expression." (PMID 33537001, 2020). "PKM2 also induces tumor angiogenesis through activation of NF-κB and HIF-1α." (PMID 33292198, 2020). "In addition, factors inducing inflammatory responses, like Peli1, Pgts2, Socs3, and Tnfrsf9, were downregulated, while an inhibitor of the NF-κB pathway (Nfkbie) was upregulated in HIF-1α-KD tumor cells." (PMID 33142239, 2020). "Besides, exosomes derived from hypoxic-treated hepatocellular cancer cells are enriched with linc-RoR that promote migration and metastasis of tumor cells via a miR-145/HIF-1α signaling pathway in vitro." (PMID 33302971, 2020). "In addition to the excellent tumor vascular targeting, the efficiency of CENPs in reversing tumor hypoxia was examined using the hypoxia-inducible factor (HIF)-1α staining assay." (PMID 33240803, 2020). "The sarcomas TME is also rich with immunosuppressive cytokines including vascular endothelial growth factor (VEGF) that, together with hypoxia-inducible factor-1 α (HIF-1α), inhibits the maturation of dendric cells and promotes M2 macrophages and Treg migration inside the tumor stroma." (PMID 32102348, 2020). "Interestingly, hypoxia through HIF-1α significantly changes the function of MDSC in TME and shifts its differentiation direction to tumor-associated macrophages (TAMs)." (PMID 33489906, 2020). "Importantly, we have shown that Ki-67 response to metformin is significantly lower in tumours with higher baseline HIF-1α, suggesting decreased metformin response in hypoxic tumours." (PMID 31819173, 2020). "Although it well established that HIF1α overexpression is associated with OVCA tumor aggressiveness, progression and metastasis, inhibiting HIF1α as a therapeutic option has yielded no success." (PMID 31700155, 2020).
tumor (continued). "Additionally, hypoxia can contribute to the immune escape of tumor cells via the upregulation of programmed cell death ligand 1 (PDL1) in a hypoxia-inducible factor-1α (HIF-1α)-dependent manner." (PMID 32974200, 2020). "Nb@IC-NPs showed good biocompatibility, which could be efficiently uptaken by A549 cells, achieving sufficient oxygen supply and the reduction of Hypoxia-inducible factor-1α (HIF-1α) expression in A549 tumor." (PMID 33292202, 2020). "Interestingly, we observed that tumors formed by circ-ERBIN op stable cells grew larger and more quick, suggesting tumor angiogenesis and HIF-1α signaling were up-regulated in these tumors." (PMID 33225938, 2020). "HIF-1α is widely overexpressed in human cancers to prevent tumor apoptosis due to oxygen depletion." (PMID 33344242, 2020). "Importantly, our data demonstrated the key role of circ-ERBIN in tumor angiogenesis and activation of HIF-1α signaling pathway in CRC progression." (PMID 33225938, 2020). "HIF-1α expression is a characteristic indicator for assessing hypoxia in tumor tissues." (PMID 33240803, 2020). "As we have known, hypoxia plays a pivotal role in cancer through the alteration of microenvironment and promoting formation of blood vessels, and hypoxia inducible factor (HIF-1α) is a master gene in mediating different hypoxia related cell processes, including tumor angiogenesis." (PMID 33225938, 2020). "Recent studies have shown that tumor cell-derived exosomes play a prominent role in the pathology of tumor metastases by using tumor-signaling pathway such as caveolin-1, HIF-1a, miR-21, miR-105, miR-210, β-catenin and oncogenic kinases (e.g., mutated EGFR, RAS and MAP kinases)." (PMID 32257377, 2020). "Tumor hypoxia has been shown to induce expression of hypoxia-inducible factor 1α (HIF1α), which is known to be integral to adaptively responding to hypoxia by targeting many genes involved in facilitating tumor survival, proliferation, invasion, and metastasis." (PMID 32451768, 2020). "In addition, HIF-1α induced the stabilization of the pHi to secure tumor cell survival and DNA replication." (PMID 32846951, 2020). "In addition, a different miRNA, namely miR-186, which decreases indirectly lactate levels through direct inhibition of HIF-1α and glycolysis, functions as a tumor suppressor of both HOS and U2 OS cell lines, inhibiting tumor cell proliferation and invasion." (PMID 32102348, 2020). "Hypoxia-inducible factor-1α (HIF-1α) plays a crucial role in the development of the tumor." (PMID 32908869, 2020). "As such, interleukin (IL)-8 (CXCL8) signaling preserves the angiogenic phenotype in HIF1-α-deficient colon cancer cells, indicating a critical role of IL-8 in tumor-associated angiogenesis, independent of VEGF." (PMID 33352897, 2020). "Hypoxia inducible factor 1α (HIF-1α) is a master gene in hypoxia-induced microenvironment, which controls the expressions of oncogene transcription and other relevant target genes that participate in tumor cell proliferation, invasion and metastasis." (PMID 33225938, 2020). "Meis1 transcriptionally regulates the expression of hypoxic tumor markers, Hif-1α and Hif-2α." (PMID 32409701, 2020). "These cells were implanted into the brains of the mice, and cells with simultaneous HIF1α and HIF2α knockout produced tumours with a larger volume than control cells, and the tumours of both groups above were larger than groups implanted with single HIF1α or HIF2α knockout cells." (PMID 33208727, 2020). "Knockdown of HIF-1α promotes ccRCC cell proliferation and xenograft tumor growth." (PMID 33251216, 2020). "HIF-1α was responsible for this upregulation as confirmed by CRISPR-engineered tumor cells." (PMID 33117401, 2020). "Activation of HIF-1α plays an essential role in the invasive process, as it regulates specific genes involved in cell motility, adhesion and invasion through invadopodia, which are critical for tumour growth and aggressiveness." (PMID 32386517, 2020).
tumor (continued). "In addition to mTOR inhibition, inhibitors of PI3K/Akt can decrease HIF-1α expression, inhibit cell proliferation, and trigger cell death, and therefore are detrimental to tumor progression." (PMID 33028364, 2020). "Collectively, our findings suggested that PVT1 could act as an oncogenic lncRNA, and promote tumor progression by regulating HIF-1A via competing with miR-519d-3p." (PMID 32201527, 2020). "It has been reported that HIF-1α could stimulate tumor angiogenesis and lymphangiogenesis, and promote metastasis and recurrence 14-17." (PMID 31892989, 2020). "Thus, the relationship between hypoxia, HIF-1α, and invadopodia formation clearly influences tumour aggressiveness." (PMID 32386517, 2020). "HIF-1α is a transcriptional activator that acts as a key regulator of the glycolysis and plays an important role in hypoxic responses, inducing the transcription of various genes responsible for tumor angiogenesis, invasion, and metastasis." (PMID 32076440, 2020). "Typically, cells will undergo apoptosis under such conditions, but tumor cells are able to upregulate both hypoxia-inducible factor 1 alpha (HIF-1α) and hypoxia-inducible factor 2 alpha (HIF-2α), which synergistically leads to the transcription of VEGF and hence the creation of more blood vessels." (PMID 32316322, 2020). "In particular, the induction of HIF-1α allows the expression of genes that promote the reprogramming of tumor metabolism towards the glycolic pathway, increasing glucose uptake, the expression of glycolic enzymes and the production of lactate, regulating the pyruvate metabolism." (PMID 32131421, 2020). "The potentially most clinical interesting CI inhibitor, metformin, also used in our study, has already shown its ability to decrease HIF-1α stabilization in various tumor backgrounds and therefore contributes to a slower tumor growth, potentially related to the suppression of VEGF." (PMID 32509579, 2020). "It is also known that a major part of the action of these two pathways, in tumor angiogenesis and development, is mediated through increasing hypoxia-inducible factor 1-alpha (HIF-1α) transcription, which is the key mediator involved in VEGF secretion in hypoxic microenvironment." (PMID 33424993, 2020). "In dogs treated by surgery and TOC, the median numbers of HIF‐1α+ tumor cells at baseline and follow‐up were 17.8 and 8.5 cells per HPF, respectively, which represents a significant decrease in the number of these cells at follow‐up when compared to baseline (P = .02)." (PMID 32267594, 2020). "Besides inflammatory cytokines extrinsically modulating PD-L1 expression, hypoxia in the tumor microenvironment selectively elevates PD-L1 expression via HIF-1α activation in melanoma, breast, lung, thyroid and prostate cancer." (PMID 33193345, 2020). "In addition, low PD-L1 expression in tumour cells correlated with high HIF-1A expression and low E-cadherin expression." (PMID 32238919, 2020). "The CI inhibitor AG311 also reduced HIF-1α stabilization and in combination with an inhibitor of the pyruvate dehydrogenase kinase, a key regulatory enzyme of oxidative metabolism, resulted in a reduced tumor growth." (PMID 32509579, 2020). "For instance, it induces HIF-1α expression, priming tumor cells for a hypoxic microenvironment." (PMID 32992699, 2020). "It is unclear if HIF-1α mediated by A3R promotes tumor progression or antitumor activity." (PMID 32351498, 2020). "Furthermore, in ischemic endothelial cells, CXCL12 gene expression in tumor cells is controlled by HIF-1α in direct proportion to reduced oxygen level." (PMID 32456359, 2020). "Based on linear relationship availability between variables and survival outcome, for OS, only CAIX blood mRNA, CAIX tissue mRNA, CAIX soluble protein, HIF1A blood mRNA, HIF1A tissue mRNA, histopathological grade, surgical status, and tumor types were eligible for modeling." (PMID 32212787, 2020).